IRF7 (interferon regulatory factor 7)
Diseases named in the same sentence as IRF7 in open-access papers (continued):
Sharing a sentence is not in itself a finding about the gene and the disease.
tumor (continued). "White arrowheads highlight irf7 expression specific to the tumor microenvironment (TME)." (PMID 39052000, 2024). "IRF7 can play either tumor suppressive or oncogenic roles in different cancers." (PMID 39329063, 2024). "IRF7 regulates the expression of inflammatory cytokines, polarizes microglia towards an M2 phenotype, fosters an immunosuppressive tumor microenvironment, and facilitates tumor growth, invasion, and immune evasion." (PMID 39384770, 2024). "It found that tumor-associated macrophages had upregulated genes regulated by IRF2, IRF7, IRF9, and STAT2, and downregulated genes regulated by Fos/Jun and IRF8, revealing decreased inflammatory response, TNF-α-induced proliferation, and reactive oxygen species production pathways." (PMID 39034998, 2024). "Activation of IRF7 inhibits various viral and bacterial infections and suppresses the growth and metastasis of some cancers, but it may also affect the tumor microenvironment and promote the development of other cancers." (PMID 37251373, 2023). "IRF7 can act as a tumor suppressor that inhibits the proliferation and metastasis of cancer cells." (PMID 37251373, 2023). "Interestingly, IRF7 can be regulated by some MicroRNAs and also affects certain MicroRNA regulators in the tumor microenvironment." (PMID 37251373, 2023). "Restoration of BCL7A hindered cell proliferation in competition cell growth assay and xenograft tumor formation in vivo modulating significantly the expression of genes such as HMGCS1, H1-0, and IRF7, which may help to explain its tumor suppressor role in AML." (PMID 36941700, 2023). "Also, differential expression analysis found that BCL7A restoration altered cell cycle pathways and modified significantly the expression of genes like HMGCS1, H1-0, and IRF7 which can help to explain its tumor suppressor role in AML." (PMID 36941700, 2023). "Moreover, pUL48, a tegument protein of HCMV, can encode DUB for the deubiquitination of TRAF6, TRAF3, IRAK1, IRF7 and STING, thereby inhibiting type I IFN responses, obtaining tumor precursor function, and promoting tumor formation." (PMID 37600809, 2023). "Importantly, we consolidates the importance of miR-762 mitigation for accomplishing the tumor-inhibitory role of circ0007360 and further links IRF7 as a downstream effector of miR-762." (PMID 35252169, 2022). "Furthermore, we identified interferon regulatory factor 7 (IRF7) as a target gene of miR-762 and performed a series of rescue experiments to validate that IRF7 is an indirect target of circ0007360 to exert its tumor-suppressive role." (PMID 35252169, 2022). "Moreover, the in vitro and in vivo tumor-suppressive roles of IRF7 were uncovered in OS and these effects were largely glycolysis-dependent." (PMID 34975316, 2022). "However, our results, at least to some extent, confirmed that IRF7 transcriptionally suppressed PKM2 expression to inhibit tumor glycolysis." (PMID 34975316, 2022). "Apart from tumor-suppressive roles, IRF7 also plays several oncogenic properties." (PMID 34975316, 2022). "Targeting IRF7 may help to reverse the abnormal differentiation of myeloid cells and thus play a role in tumor immunotherapy." (PMID 35692836, 2022). "Collectively, these data above suggest that IRF7 acts as a tumor suppressor in OS." (PMID 34975316, 2022). "Thus, our data prove that IRF7 inhibition is responsible for the tumor-promoting function directed by miR-762." (PMID 35252169, 2022). "In addition to its master role in controlling type I interferon production and immune system regulation, IRF7 acts as an oncogene or tumor suppressor, depending on the cell types used for investigations." (PMID 35252169, 2022). "Previously, we found that IRF3 and IRF7 could mediate the acquisition of new anti-tumor effector functions in macrophages." (PMID 34488791, 2021).
tumor (continued). "Furthermore, sustained activation of the IFN-β/IFNAR/IRF7 signaling axis in chemotherapy-treated ER-negative BC cells instigates a state in which tumor cells are likely controlled by immune-mediated mechanisms." (PMID 33766090, 2021). "Restoration of IRF7 inhibited bone metastasis of BC cells by inducing the production of type I IFNs, and caused an increasing of CD8+ T cells in the blood samples of 4T1 tumor-bearing mice." (PMID 34858816, 2021). "A previous study reported that silencing IRF7 could assist tumor cell to escape from the immune system, leading to increased tumor metastasis." (PMID 30948928, 2019). "This raises the intriguing possibility that some forms of dormancy occurring during tumor evolution may be due to spontaneous IRF7/IFN-β axis activation." (PMID 30546090, 2019). "Thus, enforced tumor expression of the master regulator of type I IFN signaling, IRF7, is sufficient to increase the accumulation and activation of tumor infiltrating lymphocytes, in particular, activated CD8+ T cells and NK cells." (PMID 31482136, 2019). "However, the protein expression of PDL1 was negatively correlated with that of IRF7 in the tumor tissue of SCC." (PMID 30305853, 2018). "The high expression of IRF7 in the tumor tissue of SCC may come from the tumor surrounding cells or by other mechanism like posttranslational regulation." (PMID 30305853, 2018). "Furthermore, intra-tumoral IL-12 delivery resulted in accumulation of IRF7 in tumor cells, which correlated with tumor regression." (PMID 24994117, 2014). "However, this enhanced cytotoxicity of IRF7-C435A lymphocytes was reduced by the addition of H2KB antibodies, suggesting that downregulation of antigen presentation is the main mechanism by which NOS1-mediated S-nitrosylation of IRF7 facilitates tumor escape from killing by immune cells." (PMID 41535256, 2026). "IRF7 could regulate tumor microcirculation through the regulation of NR3C1 expression under some environments could promote tumor cell proliferation by regulating the tumor microenvironment." (PMID 40406148, 2025). "Interestingly, we observed upregulation of several interferon regulatory factor (Irf) family members including irf7 and irf8 in p53EPS tumor-burdened brains, suggesting potential roles for these master regulators of inflammation on immune-related responses during p53EPS tumorigenesis in vivo." (PMID 39052000, 2024). "Furthermore, the spatial transcriptome data provided insight into the specific localization of IRF7 expression, suggesting that its effects are most pronounced in the central regions of the tumor, where immune suppression and tumor growth are actively regulated." (PMID 39492838, 2024). "Therefore, IRF7 plays an important role in tumor development and metastasis." (PMID 37251373, 2023). "Finally, our results show that tumor tissues in GBM patients highly express IRF3 and IRF7, encoding interferon regulatory factors that can lead to the transcription of caspase-11, which is important for noncanonical NLRP3 inflammasome activation, via activation of the JAK/STAT pathway." (PMID 31133717, 2019). "Moreover, up-regulated expressions of CD40LG and IRF7 may make for improved tumor cytolytic function of CIKIL-2 through type I interferon signaling." (PMID 25108500, 2014). "Knocking out Irf3, Irf7, Gsdme or Ripk3 in B16F10 tumor cells each reduced DAC’s effectiveness at inducing immune control of the tumor, which indicates that the derepression of multiple innate immune pathways helped to restore immune control." (PMID 41315764, 2026). "For example, IFIX is a DNA sensor that has anti-viral and anti-tumor activities, and MNDA regulates the transcription of IRF7 by recruiting RNA polymerase II to its promoter." (PMID 41193640, 2025). "Following immune training with KK2DP7 and tumor inoculation, TLR2 and IRF7 were significantly activated in CD11b+ cells within the non‐lymphocyte layer of the mouse spleen, accompanied by a significant increase in interferon secretion." (PMID 40145812, 2025).
tumor (continued). "Subsequently, western blot and ELISA analyses were conducted on splenic CD11b+ cells from non‐lymphoid layers of normal mice, TLR2‐/‐ mice, and IRF7‐/‐ mice following KK2DP7 training and subsequent tumor or LPS inoculation for 48 h." (PMID 40145812, 2025). "Therefore, IRF7 regulon expression may influence tumor malignant cell content." (PMID 39492838, 2024). "We assessed the density and distribution of IRF7 and IBA1 in formalin‐fixed, paraffin‐embedded tumor sections using immunofluorescence microscopy coupled with quantitative digital imaging." (PMID 39492838, 2024). "IRF7, a transcription factor belonging to the interferon regulatory factor (IRF) family, has previously been identified as a tumour suppressor across various cancer forms." (PMID 39118300, 2024). "The results revealed that Mn‐N/C plus H2O2 treatment notably stimulated high expression levels of IFNα, IFNβ, and ISGs including Irf7, Isg15, and Cxcl10 in MC38 tumor cells." (PMID 38308189, 2024). "In animals co-injected with irf7 CRISPR, we detected p53EPS tumor formation, albeit with reduced irf7 in and surrounding tumor cells, suggesting potential roles for irf7 in inhibiting p53EPS initiation in tumor cells and/or within the TME." (PMID 39052000, 2024). "It will be of interest to examine IRF7 expression and activation as well as type I IFN expression in the tumor microenvironment of pituitary tumors as well as cancers associated with elevated AIP expression." (PMID 38479600, 2024). "IRF7 inhibited the expression of S100A9, and inhibited the aggregation of granulocyte-like myeloid suppressor cells (G-MDSCs), thus suppressing tumor metastasis." (PMID 37251373, 2023). "Here, viral DNAs in the cytosol activated cGAS and downstream activated STING, IRF3, IRF7, IFN gene expression, and tumor death through the generation of antitumor CD8+ and CD4+ effectors in murine models." (PMID 38139802, 2023). "CCK8 immunofluorescence staining and EDU experiments showed that compared to controls, overexpression of both IRF7 and SHC1 promoted tumor cell proliferation." (PMID 35692836, 2022). "Therefore, the roles of IRF7 in human cancers might be tumor-specific." (PMID 34975316, 2022). "ATF7IP knockout induces interferon signaling through IRF7 and IRF9 upregulation, enhancing tumor immunogenicity and anti-tumor immunity via increased T cell activity." (PMID 36497341, 2022). "The results of the bioinformatic analysis were supported by the identification of IRF7 and SHC1 genes as hub IRGs, and the vitro assays demonstrated that IRF7 and SHC1 have a function in promoting tumor progression." (PMID 35692836, 2022). "We found that the level of IRF2, IRF6, IRF7, IRF8 and IRF9 were upregulated in tumor tissues in PC (P < 0.05)." (PMID 35012444, 2022). "We first detected the mRNA level of IRFs in PC, revealing that the level of IRF2, IRF6, IRF7, IRF8 and IRF9 were elevated in tumor tissues in PC." (PMID 35012444, 2022). "For example, IRF7 high expression potently induces CD8+ T cell responses and strengthens host immune surveillance to fight viral infection and restrict tumour metastasis; IRF9 effectively prevents CD8+ T cell exhaustion caused by over-exposure to antigens." (PMID 36741716, 2022). "Under the same study, an experiment on C57BL/6 mice with lycopene (40 mg/kg) administered intraperitoneally for 3 days resulted in the reduction of tumor volume, weight, IL-4, IL-10, gene expression of DMNT3a and methylation levels of promoters (IRF1, IRF7)." (PMID 34202203, 2021). "Specifically, IRF3, IRF7, and IRF9 were significantly upregulated in tumor tissues, whereas IRF4 was downregulated (P < 0.001)." (PMID 34488791, 2021).
tumor (continued). "Such infiltration resulted from the induction of STAT1 and IRF7, and the expression and secretion of pro-inflammatory chemokines and cytokines (CCL5, CXCL10, and interferon-γ) in tumor cells in vitro and tumor plasma in vivo." (PMID 34681622, 2021). "In this experiment, lycopene managed to enhance IFNβ, IFNγ, IRF1, IRF7, CXCL9, CXCL10 while suppressing IL-4, IL-10, DMNT3a, methylation of IRF1, IRF7 promoters and most importantly, the tumor volume." (PMID 34202203, 2021). "Additionally, overexpression of IRF7 in prostate cancer cells inhibits bone metastases through IFNI-induced NK activation, while loss of host IFNI receptor signaling in vivo blocks NK-mediated anti-tumor immune responses and results in increased cancer cell metastasis." (PMID 33801234, 2021). "The link between IRF7/IFN pathway and tumor resistance remains elusive at this point, which will be further studied." (PMID 30546090, 2019). "According to our previous study using the same tumor model, pDC, which can predominantly produce large amounts of IFN-I because of its high basal expression of IRF7, was the main producer of IFN-I in tumors." (PMID 31049360, 2019). "Consistently with the tumor suppressive role of STAT1 signaling in tumorigenesis, nuclear IRF7 protein expression was significantly reduced in GBC compared to normal gallbladder epithelium of paired samples (p < 0.001)." (PMID 30886199, 2019). "DR500 cells have a weaker activation of the IRF7/IFN response, which translates into a lesser effect on the immune response compared to MR20 tumor-bearing mice." (PMID 30546090, 2019). "The level of IRF7 was negatively correlated with those of PDL1, eIF2α, and ATF4 in the tumor tissue of SCC." (PMID 30305853, 2018). "The expression of IRF7 was negatively correlated with those of eIF2α and ATF4 in the tumor tissue of SCC." (PMID 30305853, 2018). "The expression of IFNAR1 was correlated with that of IRF1 in the tumor tissue of adenocarcinoma and those of IRF1 and IRF7 in the normal tissue of SCC." (PMID 30305853, 2018). "For spleens from tumor bearing old mice majority of the upstream regulators are either interferons (IFNγ, IFNα, IRF3, IRF7, and IFNA2) or are related to the immune system (IKBKB, CHUK, NFκB, NFκBIA, STAT3, and mir-21) and are predicted to be up-regulated." (PMID 26497558, 2015). "Through upstream regulator analysis it was predicted that several interferons, IFNγ, IFNα, IRF3, IRF7, and IFNA2, were up-regulated for spleens from old tumor bearing mice." (PMID 26497558, 2015). "Type-I IFN signaling has been recently reported to be involved in tumor metastasis, e.g., genes suppressed in bone metastasis are targets of IFN regulatory factor 7 (IRF7)." (PMID 24884733, 2014). "Eight of these immune response genes (SPP1, PDPN, IL1RN, IL6, CCL8, MDK, IRF7, and HRH4) were expressed between 1.25–1.59 fold higher in the microglia/macrophage enriched population compared to bulk tumor." (PMID 22937035, 2012). "Notable, genes involved in TGF-β signalling (SOS1, SOS2, SMAD5, LTBP3, TGFBR2, IRF7 and CREBZF) were found to be significantly (P<0.01) downregulated in the VEGFA165 tumours." (PMID 22045186, 2011). "Therefore, NOS1-induced IRF7-SNO inhibits T cell activation and T cell killing in the tumor immune microenvironment." (PMID 41535256, 2026). "This suggests that NOS1 induction of IRF7 S-nitrosylation activates antigen-presenting cells (APCs) by increasing the transcription of MHC class I and class II antigens and APM components, thereby reversing immune suppression in the tumor microenvironment." (PMID 41535256, 2026). "In addition, the inhibition of IRF4, IRF5, IRF7, and IRF8 decreases the survival of PC patients, indicating these IRFs probably act as anti-tumor factors in PC." (PMID 39384770, 2024). "Analysis of immune infiltration using TIMER v2.0 database revealed a positive correlation between IRF7 and the infiltration levels of M1 macrophages, while showing a negative correlation with tumour cell purity." (PMID 39118300, 2024).
tumor (continued). "In addition, molecular network regulatory maps showed that apoptosis pathway-related genes (e.g., IRF7 and DDIT3) in tumor cells showed overall activation after NCAPD3 inhibition." (PMID 38711992, 2024). "Moreover, tumor-derived TGF-β and TNF-α synergistically inhibit IFN-I and TNF-α production through blocking interferon regulatory factor 7 (IRF7) expression and nuclear translocation." (PMID 37817484, 2023). "IRF1 has tumor suppressor and antimicrobial functions, whereas IRF7 is required for the activation of the IFN-α and -λ gene transcription that requires the IRF3-IRF7 activated heterodimers." (PMID 37298304, 2023). "Therefore, we suggested that the level of IRF3, IRF6, IRF7, IRF8 and IRF9 were upregulated in tumor tissues of PC." (PMID 35012444, 2022). "Tumor cell-derived DNAs can be detected by one of the major DNA sensors, cyclic GMP-AMP synthase (cGAS) (a cytosolic DNA sensor), which activates STING and then the TBK1 (the major kinase for IRF7 and IRF3 activation) pathway, thus inducing IFN-1 expression." (PMID 31049360, 2019). "To do this we interrogated the tumor expression of IRF9, a key transcription factor that is induced by IFN and forms part of the ISGF3 complex, responsible for stimulation of many IRGs—including IRF7." (PMID 31482136, 2019). "Upregulation of IRF7 in treated cancer cells promoted resistance to chemotherapy, reduced cell growth and induced switching of the response from a myeloid derived suppressor cell-dominated immune response to a CD4+/CD8+ T cell-dependent anti-tumor response." (PMID 30546090, 2019). "Previously, we have shown that IFN-I-inducible 2′-5′ oligoadenylate synthetase-like 1 (OASL1), a specific inhibitor of IRF7 (master transcription factor (TF) for IFN-I) translation, negatively regulates IFN-I production upon tumor challenge, similar to those of viral infections." (PMID 31049360, 2019). "The protein expression of IRF7 in the tumor tissue of SCC was higher than those in the corresponding normal tissue and the tumor tissue of adenocarcinoma." (PMID 30305853, 2018). "Furthermore, HCMV deubiquitinase acquires pro-tumor functions by inhibiting PRR-mediated type I interferon via deubiquitination of TRAF6, TRAF3, IRAK1, IRF7 and STING." (PMID 28981114, 2017). "Multigene expression analysis by qRT–PCR revealed a strong correlation between the expression of human monocytic markers CD14 or CD16 and diverse IFN-I-related genes such as IFNB1, USP18 and IRF7, indicating that human monocytic infiltrates can produce IFN-I within human tumour tissues." (PMID 28248314, 2017). "Consistently, we have found 3 tumor suppressive genes which were significantly up-regulated in CIKIL-2 including tumor necrosis factor ligand superfamily member 10 (TNFSF10), CD40 ligand (CD40LG) and interferon regulatory factor 7 (IRF7)." (PMID 25108500, 2014). "In contrast, the promoter hybridization signal for the IRF7 gene (as negative control) was similar between tumor and non-tumor samples." (PMID 24243817, 2013). "Differences in gene expression profiles of tumor cells isolated from matched pairs of primary tumors and bone metastases revealed that a high number of IFN-related genes were down-regulated in bone metastases including irf7." (PMID 23269924, 2012). "vRNA replication in microglia triggered selective interferon (IFN) regulatory factor (IRF) 3/IRF7 transcriptional programs in the relative absence of NFκB-driven proinflammatory cytokine responses and elicited robust phagocytosis of both tumor cells and amyloid-beta." (PMID 41993267, 2026). "These exploratory findings require more detailed study of the LMP1/IRF7 pathway, if anti-viral or anti-cancer immunity is mediated by ISG15, and to determine whether type I IFNs are exerting a pro- or anti-tumor effect in BL tumors." (PMID 36878637, 2023).